ATG16L1 (autophagy related 16 like 1)
Diseases named in the same sentence as ATG16L1 in open-access papers (continued):
Sharing a sentence is not in itself a finding about the gene and the disease.
infection (66 papers, 2008 to 2026). The state of being infected such as from the introduction of a foreign agent such as serum, vaccine, antigenic substance or organism. "Previous studies have demonstrated that the Salmonella effector SopF disrupts the infection-induced association between V-ATPase and ATG16L1." (PMID 41508142, 2026). "In mice, reduced ATG16L1 expression results in preterm birth upon an inflammatory stimulation and increases susceptibility to infection in ATG16L1-deficient placentas." (PMID 40791986, 2025). "Placental explants deficient in ATG16L1 exhibit heightened susceptibility to infections caused by pathogenic E. coli." (PMID 39628569, 2024). "After 4 h of infection, invasion of the ATG16L1-deficient cells by C. albicans was slightly, but significantly increased (50.8%) compared to control cells (39.5%)." (PMID 35086419, 2022). "Caspase-8 ubiquitination was elevated at K169 in both WT and cKO early post-infection, but was sustained through the late timepoint only in ATG16L1-deficient BMDMs." (PMID 34085925, 2021). "In NOD2 overexpressing Caco-2 cells, AIEC infection led to a stronger increase in ATG16L1 protein expression associated with a decrease in AIEC survival and of pro-inflammatory cytokines release compared to WT Caco-2 cells." (PMID 32466328, 2020). "Namely, upon infection, internalized bacteria cause damage to the residing vacuole, which is sensed by the vacuolar ATPase that then recruits ATG16L1 to initiate xenophagy." (PMID 31849988, 2019). "Fourth, we show that Atg16l1-deficient mice gave birth prematurely upon an inflammatory stimulus and their placentas were significantly less able to withstand infection." (PMID 28018968, 2016). "Together, our findings suggest that a low level of autophagy, decreased expression of ATG16L1, and possibly subclinical infection in the placenta are associated with early PTB." (PMID 28018968, 2016). "We have shown that loss of Atg16L1 protects mice against infections of the urinary tract and the intestine." (PMID 28018968, 2016). "Third, we demonstrate that higher levels of autophagy and ATG16L1 in human trophoblasts were associated with increased resistance to infection." (PMID 28018968, 2016). "These placentas came from women with increased white blood cell counts, suggesting that loss or dysfunction of ATG16L1 can synergize with inflammation, and possibly infection, to cause PTB." (PMID 28018968, 2016). "At present, it can only be speculated how ATG16L1 T300A variant may confers risk or protection from infection, depending on the nature of the pathogen and the typical duration of infection." (PMID 25159710, 2014). "Therefore, we applied our knock-down/reconstitution system, including variant specific ATG16L1 reconstitution, followed by infection with S. Typhimurium infection and measured the percentage of GFP-LC3 captured bacteria." (PMID 18852889, 2008). "However, whether autophagic flux in general, and ATG16L1 in particular, contributes to placental susceptibility to infection and PTB is unknown." (PMID 28018968, 2016). "However, Atg16L1 deficiency in many other tissues leads to increased susceptibility to infection." (PMID 28018968, 2016). "MDMs trained with BS and BL restored their ability to upregulate NPC2, MAP1LC3, and ATG16L1 after infection with M. tuberculosis." (PMID 41488622, 2025). "To analyze IAV entry into MEFs early in infection, we performed in vitro assessments of viral entry to confirm our previous work that the WD domain of ATG16L1 slows endocytosis and nuclear entry of IAV." (PMID 40143422, 2025). "Infection induces an increase in cellular PI4P levels in an ATG16L1-dependent manner, while ATG16L1 relocalizes to ER membranes upon infection." (PMID 40668844, 2025). "In V2 and KO cells, ATG16L1 expression was lower in the WT group compared to the uninfected controls, whereas infection with espF-deletion strains reduced this decline." (PMID 41522448, 2025).
infection (continued). "We found that the C3 deposition protected host cells against infection by restricting intracellular staphylococcal growth in an ATG16L1-dependent manner." (PMID 39310788, 2024). "The Togaviridae family member Sindbis virus (SINV) induces SGs formation in the early stages of infection, a process requiring autophagy-related protein 16-like 1 (ATG16L1), but then, the SGs disappear in the late stages of infection." (PMID 37205103, 2023). "In fact, in vivo models of infection highlight the role of xenophagy in intracellular pathogen clearance, as knocking down essential autophagy genes, like Atg5 or Atg16L1, increases bacterial load in mice infected with Salmonella59,60." (PMID 40395298, 2023). "Conversely, excision of other core autophagy genes including Atg5, Atg7, Atg14, and Atg16l1 from the mice macrophages showed moderate to severe level vulnerability to pathogen infection and bacterial burden." (PMID 37180758, 2023). "In contrast, Atg16L1 silencing resulted in similar intracellular numbers following infections with all bacterial strains." (PMID 35467412, 2022). "CASM is activated by engulfment (endocytosis, phagocytosis), agonists (STING, TRPML1), and infection (influenza), dependent on K490 in the ATG16L1 WD40-domain." (PMID 35511089, 2022). "Contribution of some autophagy-related proteins (ATG16L1, ATG5, and ATG12) in lysosomal exocytosis was recently highlighted in the context of host cell infection by the Gram-positive pathogenic bacterium Listeria monocytogenes." (PMID 35086419, 2022). "There were no marked changes noted in the expression of Becn1, Atg5, Atg7, Atg12, Atg16l1 or Atg16l2 both before and 6 h after infection." (PMID 35903351, 2022). "Infection of RAW 264.7 cells transfected with a small hairpin inhibitory RNA targeting ATG16L1 (shAtg16L1 macrophages [Mφ]) demonstrated limited autophagy even during Δ51 infection." (PMID 35467412, 2022). "(A, B) Comparison of CFUs per well from three independent infection experiments in the presence of 4 μg/ml Erastin using BMDM preparations from three different Atg16l1-WT (A) or Atg16l1-cKO (B) mice." (PMID 34085925, 2021). "(D, E) Comparison of CFUs per well from four independent infection experiments in the presence of 150 μM BHA using BMDM preparations from four different Atg16l1-WT (D) or Atg16l1-cKO (E) mice." (PMID 34085925, 2021). "(B) Comparison of colony forming units (CFUs) per well from independent infection experiments using BMDM preparations from Atg16l1-WT or Atg16l1-cKO mice." (PMID 34085925, 2021). "In this study, we investigated the role of ATG16L1 in myeloid cells in response to infection by virulent S.flexneri (strain M90T)." (PMID 34085925, 2021). "It will be interesting to see if the WD and linker domains of ATG16L1 limit infection by other microbes at epithelial barriers in vivo, particularly infection of the respiratory tract by SARS‐CoV‐2." (PMID 33586810, 2021). "Thus, ATG16L1 deficiency and S.flexneri infection might each independently elevate ROS levels, with ATG16L1 deficiency further driving a compensatory increase in the redox regulators during infection to maintain macrophage viability." (PMID 34085925, 2021). "And SopF can target ATP6V0C for ADP-ribosylation on Gln124, thereby blocking bacterial autophagy and infection-induced recruitment of ATG16L1 by the V-ATPase." (PMID 31849988, 2019). "On the other hand, Atg16L1 mutant mice mount an enhanced monocyte response that confers resistance to infection by C. rodentium, a striking contrast to observations made in the Nod2 mutants." (PMID 30235350, 2018). "These and other intestinal pathologies in Atg16L1 mutant mice depend on infection by murine norovirus (MNV), raising the possibility of a virus–gene interaction in IBD." (PMID 30235350, 2018). "In order to establish the level of parasite clearance in Atg16L1 knock down compared to control siRNA-treated cells, the percentage infected cells at 18h post infection in HUVEC was determined." (PMID 27875583, 2016).
infection (continued). "ATG16L1, a reported susceptibility gene for IBD, controls autophagy, a crucial process in the resistance against infection and removal of intracellular microbes." (PMID 24155895, 2013). "Release of cytokines such as IL-1β and IL-18 after LPS or infection with non-invasive bacteria such as E. coli was significantly increased in Atg16L1-null macrophages." (PMID 20107532, 2009). "Thus, we believe that patients with the ATG16L1*300A allele are likely to be fully competent for the homeostatic functions of autophagy, yet may exhibit altered responses to bacterial components and infection in the gut milieu, where antigen burden is high." (PMID 18852889, 2008). "Our findings suggest that the decrease of ATG16L1 in septic patients might lead to a more serious infection." (PMID 38780016, 2024). "The Atg16l1 (Δ WD) mouse model lacks the WD40 domain required for LAP and has been widely used to study the effects of LAP deficiency and autophagy on tissue homeostasis and response to infection." (PMID 38827330, 2024). "In vitro cell experiments confirmed that the absence of ATG16L1 increased the susceptibility of fetal syncytiotrophoblasts to infection." (PMID 38371923, 2024). "Furthermore, Atg16L1 contributes to modulating the extent of the innate immune response to injuries or infection, with an anti-inflammatory role." (PMID 36901549, 2023). "Silencing RNF213, Atg5, Atg7, Atg16L1, or galectin or pharmacological inhibition of autophagy increases Salmonella replication, suggesting that autophagy and degradation in lysosomes protect cells from infection." (PMID 36288298, 2022). "There are however examples where the WD domain of ATG16L1 has roles during infection that are separate from conventional autophagy, and this may be true also for control of IAV." (PMID 33586810, 2021). "Nevertheless, it is not possible to exclude the possibility that removal of the WD and linker domains of ATG16L1 has a minor effect on canonical autophagy that might affect infection “in vivo”." (PMID 33586810, 2021). "As expected, ATG5, Beclin-1, ATG7 and ATG16L1 deficiency led to impaired conversion of endogenous LC3-I to LC3-II and decreased number of LC3 puncta following SH0165 infection." (PMID 31106159, 2019). "Here we show that, following SINV infection, ATG16L1 is required for the efficient phosphorylation of eIF2α, for high levels of viral protein synthesis and for the formation of the single perinuclear SG containing capsid seen early in infection." (PMID 31905741, 2019). "To further assess the requirement for ATG16L1 in protecting the placental syncytium from infection, we used Atg16L1-hypomorphic (Atg16L1HM) mice, which display compromised autophagic activity in numerous tissues but no obvious phenotypic abnormalities in the absence of infection/injury." (PMID 28018968, 2016). "Additionally, we show in mice that ATG16L1 is required to combat placental infection and that reduced expression of ATG16L1 leads to PTB and increased infection susceptibility in atg16l1-deficient placentas." (PMID 28018968, 2016). "However, our findings, along with other reports, demonstrate that mutations or absence of Atg7, Atg4b, LC3b, or Atg16L1 can trigger a protective response against the infection." (PMID 39971913, 2025). "Interestingly, the absence of ATG16L1 did not change the susceptibility of cytotrophoblasts to infection." (PMID 38371923, 2024). "Furthermore, ATG16L1 plays a protective role in the process of infection." (PMID 38780016, 2024). "However, impaired expression of CD-associated genes ATG16L1 or IRGM in THP-1 macrophages and NOD2 in NOD2−/− murine peritoneal macrophages led to an increased AIEC intracellular replication and to the secretion of IL-6 and TNF-α upon AIEC LF82 infection." (PMID 32466328, 2020).
infection (continued). "Interestingly, similarly to ATG16L1 and LC3, which associate with both QIRs at 2 weeks post-infection and with IBCs at 6 h post-infection, we found that Rab35 also colocalized with immature IBCs at 6 h post-infection." (PMID 26248231, 2015). "Similar results were obtained by knocking down the autophagic ATG16L1 protein, also found enriched in the vicinity of RAB11A upon infection in our proximity labeling experiments, and known to be involved in PI4P turnover." (PMID 40668844, 2025). "ATG16L1 is a crucial autophagy related protein, can be recruited by NOD1 receptor to the membrane at the infection site." (PMID 41000381, 2025). "PcLVs display LC3 on single membranes are transiently induced after 1 h of infection and are dependent on several autophagy-related factors including SQSTM1, CALCOCO2, ATG5, and C-terminal WD domain of ATG16L1." (PMID 40910070, 2025). "In nonselective macroautophagy, various external stimuli including pathogen infection, nutrient deprivation, and radiation therapy enhance autophagy by upregulating autophagy mediators such as ATG3, ATG5, ATG12, and ATG16L1." (PMID 37180758, 2023). "Of note, CAPRIN1 interacts with ATG16L1 and G3BP1 in uninfected cells, and they are relocalized to MNV RC upon infection." (PMID 37052473, 2023). "We showed that several autophagy-related proteins (LC3, ATG16L1, and WIPI2) are recruited to C. albicans invasion sites during infection of epithelial cells, including intestinal epithelial cells (cell line and gut explants)." (PMID 35086419, 2022). "It is known that LC3 recruitment during infection is triggered by TLR signaling through Rubicon and ROS production and can be mediated by the V-ATPase-ATG16L1 axis, which senses a rise in vacuolar pH." (PMID 36288298, 2022). "Following infection with IAV strain PR8, the V1A subunit of the v-ATPase co-immunoprecipitated with endogenous ATG16L1." (PMID 34706226, 2021). "Impaired ATG16L1, IRGM or NOD2 expression in macrophages increases intracellular AIEC with enhanced secretion of IL-6 and TNF in response to infection." (PMID 33468624, 2021). "To confirm that this is important for v-ATPase-ATG16L1 interaction, we reconstituted HCT116 ATG16L1−/− cells with FLAG-tagged ATG16L1 wild-type (WT) or K490A mutant and tested for v-ATPase interaction in PR8 infection." (PMID 34706226, 2021). "H37Ra infection leads to downregulation of miR-106a in a time- and dose-dependent manner and concomitant upregulation of its three targets (ULK1, ATG7, and ATG16L1) in THP-1 macrophages." (PMID 33505399, 2020). "Then we evaluated virulent F. tularensis SchuS4 infection of THP-1 cells in which six top hit genes (TNFRSF9, SERPINI1, HLA-DBR1, PLEK2, ATG5 and ATG16L1) were knocked down by individual lentiviral shRNA." (PMID 22359626, 2012). "At the same time, release of DNA, either from M.tb or mitochondria responding to infection, can activate the cGAS/STING pathway, leading to type 1 IFN production and noncanonical recruitment of LC3 to endolysosome membranes via the V-ATPase-Atg16L1 axis." (PMID 36288298, 2022). "Similar analysis of the infected datasets revealed the dynamic nature of the macrophage response to infection, irrespective of ATG16L1 genotype." (PMID 34085925, 2021). "To verify that DCAP-mediated reduction of intracellular infection actually derived from a DCAP-dependent blockade of autophagy, we repeated the UPEC infection in BECs in which the expression of essential autophagy protein, ATG16L1, was silenced by siRNA." (PMID 30006504, 2018). "Immunofluorescence confocal microscopy analysis and quantification show that ~80% of mycobacteria are decorated with Beclin-1 and Atg16L1 but not with ULK1 at 2 h post-infection." (PMID 27242971, 2016). "However, upon infection with IAV, only ATG16L1 was required for the accumulation of perinuclear autophagosomes and the translocation of LC3 to the plasma membrane." (PMID 24528869, 2014).
infection (continued). "Intriguingly, IL-1β release after infection with invasive bacteria such as Salmonella typhimurium was not increased in Atg16L1-null macrophages." (PMID 20107532, 2009). "Loss of ATG16L1 in CTBs, however, did not alter CTB susceptibility to infection (data not shown)." (PMID 28018968, 2016). "Importantly for infection studies, the ΔWD mice do not have the upregulated IFN-I signaling and inflammasome activation observed in mice lacking full length ATG16L1 in macrophages." (PMID 40910070, 2025). "The requirement of autophagy-initiation proteins ULK1, Beclin 1, and ATG14L and PI3-kinase activity but not elongation proteins ATG5, ATG16L1, ATG4B, ATG7, and LC3B suggested Brucella selectively co-opts autophagy-initiation complexes to subvert host clearance and promote infection." (PMID 38376367, 2024). "In WT macrophages, infection with K12, LF82, or mAIEC resulted in enhanced conversion of LC3B into its lipidated form (LC3B-II) and a decrease of p62, indicating autophagy activation, while levels of ATG16L1 were not affected." (PMID 33563644, 2022).